TIMP2 (TIMP metallopeptidase inhibitor 2)
Diseases named in the same sentence as TIMP2 in open-access papers (continued):
Sharing a sentence is not in itself a finding about the gene and the disease.
multiple myeloma (5 papers, 2021 to 2025). "Nevertheless, the overall diagnostic performance of IGFBP-7 and TIMP-2 remains consistent across studies, underscoring their reliability as biomarkers for renal dysfunction in multiple myeloma." (PMID 40369504, 2025). "The high serum amylase, IGFBP7/creatinine, and TIMP2/creatinine levels observed in cases (p<0.001 for all) point to metabolic and renal disruptions, which are key complications in myeloma." (PMID 40369504, 2025). "This study demonstrates the diagnostic and prognostic value of PVR (gene expression and serum protein levels), serum amylase, and urinary biomarkers (IGFBP-7 and TIMP-2) in multiple myeloma (MM)." (PMID 40369504, 2025). "TIMP-2 is predominantly synthesized by the distal tubule, however, extrarenal production of TIMP-2 has been linked to the development of myeloma." (PMID 38708150, 2024). "The study’s objective was to evaluate the utility of urinary IGFBP-7, urinary TIMP-2, and serum transgelin levels as biomarkers for the prediction of renal impairment in patents with multiple myeloma." (PMID 38708150, 2024). "Bone marrow mesenchymal stem cells derived exosomal miR-483 increased multiple myeloma’s malignant progression by inhibiting TIMP2 expression, and the inhibition of miR483 increased expression of p21 and downregulated the expression of c-Myc and Bcl-2." (PMID 36980601, 2023). "The distal tubule is a major source of TIMP-2, though extra-renal sources related to the progression of myeloma are also possible." (PMID 34946293, 2021). "When investigating TIMP-2 as a kidney injury biomarker in myeloma, it is necessary to consider the involvement in tumorigenesis, disease progression, and formation of osteolytic lesions." (PMID 34946293, 2021). "To investigate the association between PVR expression, serum amylase, IGFBP-7, and TIMP-2 with the survival outcomes of multiple myeloma (MM) patients, we analyzed the overall survival (OS) and progression-free survival (PFS) in relation to PVR expression status." (PMID 40369504, 2025). "The utility of the IGFBP-7 and TIMP-2 assay in multiple myeloma is unknown, and our findings serve as a preliminary report on their relationship with renal impairment." (PMID 34946293, 2021). "Although we did not observe urinary TIMP-2 to correlate with eGFR or FLCs, other studies have focused on TIMPs in MIDD and AL amyloidosis, revealing different roles in pathogenesis, even though both diseases are caused by FLC deposition." (PMID 34946293, 2021).
osteoarthritis (5 papers, 2009 to 2025). A noninflammatory degenerative joint disease occurring chiefly in older persons, characterized by degeneration of the articular cartilage, hypertrophy of bone at the margins and changes in the synovial membrane. "In addition, knockout study revealed that loss of TIMP2 promoted angiogenesis, thereby accelerating osteoarthritis, confirming the anti-angiogenic role of TIMP2/3." (PMID 36494333, 2022). "MMP-3, MMP-9, and MMP-13 levels increased in animals induced with osteoarthritis, but the TIMP-2 level was shown to decline." (PMID 32189997, 2020). "MiR-483 is known to target tissue inhibitors of metalloproteinases 2 (TIMP2), and a recent study suggests that inhibition of miR-483-5p by intra-articular injection of antago-miR-483-5p could prevent the onset of osteoarthritis (OA) pathogenesis by targeting Matrilin 3 (Matn3) and TIMP2." (PMID 36980601, 2023). "Notably, several other hub genes and genes associated with upstream regulators highlighted in our study—such as TIMP2, POSTN, and CHI3L1—are also critical regulators of ECM remodeling in other degenerative and fibrotic conditions, including osteoarthritis." (PMID 40565255, 2025). "TIMP-2, TIMP-3, and TIMP-4 are elevated in patients with osteoarthritis, while TIMP-1 is decreased." (PMID 32189997, 2020).
pulmonary disease (5 papers, 2014 to 2022). "Interesting, BALF MMP-2 and TIMP-2 showed a high sensitivity and specificity in predicting the malignant nature of pulmonary disease in both derivation cohort and validation cohort." (PMID 29113325, 2017). "Here, we outline the known roles of the most abundant TIMP, TIMP2, in pulmonary diseases but also discuss future perspectives in TIMP2 research that could impact the lungs." (PMID 36624735, 2022). "The link between TIMP2 and LRP1 could be relevant to pulmonary diseases." (PMID 36624735, 2022).
sarcoma (5 papers, 2013 to 2022). A usually aggressive malignant neoplasm of the soft tissue or bone. "Reverse zymography revealed upregulation of TIMP-2 activity with NM treatment in both sarcoma cell lines in a dose-dependent manner." (PMID 23661254, 2013). "Furthermore, the NM demonstrated dose-dependent decrease in MMP secretion and increase in TIMP-2 secretion by all sarcoma cell lines." (PMID 23661254, 2013). "Table I provides an overview of the u-PA, MMP and TIMP-2 activity in the tested sarcoma cell line." (PMID 23661254, 2013). "Table Iprovides an overview of the tested pediatric sarcoma cell line u-PA, MMP and TIMP-2 activities." (PMID 23900236, 2013).
squamous cell carcinoma (5 papers, 2008 to 2022). A carcinoma arising from squamous epithelial cells. "Downregulation of p38 activity increased TIMP-2 production in squamous cell carcinoma." (PMID 18474097, 2008). "In squamous cell carcinoma H1703 cells, at 24 h, MMP-2, MMP-9, TIMP-1, and TIMP-2 in the MG showed higher expression than in the CONT." (PMID 31601869, 2019). "However, BALF TIMP-2 was not significant increased among patients with adenocarcinoma or squamous cell carcinoma, thus the ROC analysis was not performed in those patients." (PMID 29113325, 2017).
tendinopathy (5 papers, 2016 to 2023). "TIMP2 expression was significantly elevated in the tendinopathy group compared to the intact tendons and acute ruptures." (PMID 29385715, 2018). "We did not observe any changes in other matrix proteins or tissue inhibitors of metalloproteinases (TIMP1 and TIMP2) therefore, in the context of tendinopathy, MMP3 may regulate inflammation in addition to influencing matrix remodelling." (PMID 30728384, 2019). "Evidence on TIMPs showed that TIMP-1 expression is briefly augmented (compensation) after acute tendon tear and reduced in tendinopathy, whereas TIMP-2, TIMP-3, and TIMP-4 are downregulated in both tendinopathy and tears." (PMID 36830637, 2023).
type 2 diabetes (5 papers, 2010 to 2025). "Collectively, these findings highlight TIMP-2 as a promising marker of metabolic dysfunction, particularly in the setting of MAFLD and type 2 diabetes, further supporting its diagnostic value in clinical practice." (PMID 41357032, 2025). "Also high levels of MMP-9 and TIMP-2 have been found in patients with an acute coronary syndrome and type 2 diabetes, probably reflecting an abnormal extracellular matrix metabolism in these patients." (PMID 20809989, 2010). "In line with that, physical exercise has a positive effect on ECM remodeling in patients with diabetes type 2 by influencing expression of MMP-2 and its tissue inhibitor TIMP-2." (PMID 31108840, 2019). "For the further mechanism studies, the target genes that efficiently bound to miR-483-5p were TIMP2 and MAPK1, and this conclusion was also corroborated by an RNA pull-down assay, hinting that miR-483-5p might participate in the regulation of type 1 and type 2 diabetes through TIMP2 and MAPK1." (PMID 33692334, 2021).
aortic aneurysm (4 papers, 2016 to 2025). A ruptured aneurysm located in the wall of the proximal portion of the descending aorta proceeding from the arch of the aorta. "TIMP2 inhibits the activity of MMP2, but it is also participatory in indirect activation of MMP2 through association with MMP14 that may promote cancer progression and, more importantly in the context of DSLD, aortic aneurysm development." (PMID 33028365, 2020). "Several studies have reported decreased expression of TIMP2 in the aorta from TAD and aortic aneurysm patients." (PMID 39022686, 2024).
atrial fibrillation (4 papers, 2011 to 2020). A disorder characterized by an electrocardiographic finding of a supraventricular arrhythmia characterized by the replacement of consistent P waves by rapid oscillations or fibrillatory waves that vary in size, shape and timing and are accompanied by an irregular ventricular response. "Recently, alterations in the expression of Timp2 and Mmp2 have been shown to be associated with atrial fibrillation in different respects, with the latter enriched in left atrium in two out of three of our datasets." (PMID 22039477, 2011). "Mitral TIMP2 staining was associated with LAD, LVEDD, severity of MR, and history of the following: RHD, infective endocarditis, chordae tendinae rupture, atrial fibrillation, fever, major mitral disease, LAD, and LVEDD." (PMID 24475101, 2014).
cardiac arrest (4 papers, 2018 to 2025). Cessation of breathing and/or cardiac function. "The performance of [TIMP-2]·[IGFBP7] was prospectively analysed in 48 patients with shock following out-of-hospital cardiac arrest (OHCA)." (PMID 29751827, 2018). "The study aimed to see if measuring urine [TIMP-2] × [IGFBP-7] levels immediately after cardiac arrest might reliably predict the onset of severe AKI (KDIGO stage 3) within 48 h of ICU admission." (PMID 39001241, 2024). "Several studies have reported that urinary [TIMP-2] × [IGFBP-7] predicts the development of AKI after major surgery, emergency department admission, out-of-hospital cardiac arrest, and in critically ill patients." (PMID 31315590, 2019).
cerebral aneurysms (4 papers, 2015 to 2023). "In a rat cerebral aneurysm model, researchers found that TIMP-1 and TIMP-2 predominantly exist in VSMCs and exhibit high expression levels within cerebral aneurysms." (PMID 37925414, 2023). "Therapies targeting MMP-9 and TIMP2 may be promising candidates in efforts to prevent the growth and rupture of cerebral aneurysms." (PMID 27349749, 2016). "Additionally, TIMP-1 and TIMP-2 were shown to have a protective role for the progression of cerebral aneurysms, which suggests that TIMPs may help prevent the degradation of ECM and rupture of cerebral aneurysms." (PMID 30518145, 2018).
cerebral infarction (4 papers, 2018 to 2022). An ischemic condition of the brain, producing a persistent focal neurological deficit in the area of distribution of the cerebral arteries. "Single nucleotide polymorphisms that cause protein structural defects or affect TIMP-2 transcription efficiency can cause cerebral infarction or cerebral hemorrhage by affecting the balance between TIMP-2 and MMP-2." (PMID 29435135, 2018). "Therefore, regulation of TIMP-2 expression by DNMT inhibitor treatment in ischemic stroke may contribute to neuroprotective mechanisms by preventing the mitochondrial dysfunction that occurs after cerebral infarction." (PMID 36142283, 2022). "In this study, vx-765 treatment enhanced the expression levels of TIMP-1 and TIMP-2 but reduced the expression levels of MMP-1, MMP-2, MMP-3, and MMP-9 proteins after cerebral infarction." (PMID 33584203, 2020).
cognitive deficits (4 papers, 2020 to 2023). "Compared to the CU reference group, cognitive impairment at the MCI stage was associated with increased levels of TIMP-2 and TIMP-4, whereas the dementia stage was associated with increased levels of MMP-10 and TIMP-2." (PMID 37221606, 2023). "In addition, systemic TIMP2 neutralization with anti-TIMP2 IgG alters spatial memory in young mice, while administration of recombinant TIMP2 reversed the cognitive deficits in aged mice." (PMID 38015626, 2023). "Although how young blood reversed aging-induced cognitive defects is not clear, a recent study suggests that tissue inhibitor of metalloproteinases 2 (TIMP2) plays a critical role in mediating human cord plasma-induced beneficial effects on synaptic and cognitive function in aged mice." (PMID 32677986, 2020).
congenital heart disease (4 papers, 2014 to 2025). A heart disease that is present at birth. "The same may be true for the missing difference in the baseline [TIMP-2]•[IGFBP7] levels in patients with either immature kidneys (<2 years) or venous congestion resulting from congenital heart disease." (PMID 25343505, 2014). "The results of our study and those of related studies indicate that MMP-2, MMP-9, TIMP-1, and according to our findings, also TIMP-2, play a role in the etiopathogenesis of VSD and other congenital heart anomalies in humans." (PMID 39466144, 2025). "Urinary [TIMP-2]•[IGFBP7] represent sensitive, specific, and highly predictive early biomarkers for AKI after surgery for congenital heart disease." (PMID 25343505, 2014).
esophageal cancer (4 papers, 2016 to 2022). A primary or metastatic malignant neoplasm involving the esophagus. "In previous study, we prepared a TIMP2-based recombinant protein and its enediyne-integrated analog, and subsequently, demonstrated their antitumor efficacy against human esophageal carcinoma xenografts in athymice mice." (PMID 29250984, 2018). "Moreover, in esophageal carcinoma TIMP-2 expression is negatively correlated with lymph node metastasis via inhibition of MMPs32." (PMID 31591386, 2019). "As our previous study reported, the TIMP2-based recombinant protein LDP-TIMP2 (LT) and its enediyne-integrated analog LDP(AE)-TIMP2 (LTE) that targets MMP-14/MMP-2 were effective against human esophageal carcinoma xenograft model in nude mice." (PMID 29250984, 2018).
gallbladder carcinoma (4 papers, 2013 to 2017). "It has been reported that NCTD decreased the ratio of MMP2 to TIMP2 and reduced cellular mortality, exerting anti-invasive activity in human gallbladder carcinoma cells." (PMID 23825538, 2013).
Hepatic steatosis (4 papers, 2017 to 2023). Steatosis is a term used to denote lipid accumulation within hepatocytes. "When hepatic steatosis develops, HSCs are activated and express several fibrosis markers in vitro, such as TGF-β, TIMP-1, TIMP-2, and matrix-metallo-proteinase-242." (PMID 28623272, 2017). "Downregulation of miR-483 in the NAFLD mouse model increased TIMP2 and TGF-β expression, whereas down-regulation of miR-483 in the AFLD mouse model increased TGF-β expression but not TIMP2, indicating that miR-483/TIMP2 axis differentially regulated in fatty liver disease." (PMID 36980601, 2023).
ischemic stroke (4 papers, 2014 to 2023). A stroke disorder caused by obstruction of blood flow to the brain, due to thrombotic (local blood clot formation) or embolic (due to a blood clot or other material traveling from another site) event. "Tissue inhibitor of metalloproteinase 2 (TIMP2) is a crucial endogenous inhibitor of matrix metalloproteinase-2 (MMP-2), and its expression changes are associated with the development of ischemic stroke and intracerebral hemorrhage." (PMID 37178321, 2023). "Third, besides IGF-1, DPSC-CM contains the TIMP-1 and TIMP-2 which were associated with inhibition of matrix metalloproteinase (MMP) protein levels, thereby restoring BBB integrity and improving cerebral edema following ischemic stroke." (PMID 36181630, 2023). "Since the MMP2 inhibitor TIMP2 blocked oxidative stress-induced apoptosis in a mouse model of ischemic stroke, and showed high endogenous levels in primary hucMSCs in our work, we hypothesized its cardioprotective effect in MI injury." (PMID 31182988, 2019). "Therefore, SNPs that lead to structural defects or modify the transcription rate of TIMP-2 could affect BBB breakdown and thereby influence the magnitude and/or incidence of ischemic stroke and intracranial hemorrhage." (PMID 25280484, 2014).
meningioma (4 papers, 2020 to 2024). A generally slow growing tumor attached to the dura mater. "Among the tissue inhibitors of metalloproteinases, we determined a statistically significant downregulation of the gene TIMP4 (−11.2) in meningiomas and TIMP2 (−2.0) in astrocytomas." (PMID 38474106, 2024). "NBAS, TIMP2, and NCK1 were few of the key proteins found to be altered in Atypical meningiomas." (PMID 32974197, 2020).
nasopharyngeal carcinoma (4 papers, 2015 to 2024). A carcinoma arising from the nasopharyngeal epithelium. "TIMP-2 upregulation was linked to metastasis via MMP-2 inactivation in nasopharyngeal carcinoma." (PMID 32560557, 2020). "Tissue inhibitor of metalloproteinase-2 (TIMP2) is an upstream gene of MMP2, and the imbalance of MMP2/TIMP2 may have prognostic value for nasopharyngeal carcinoma." (PMID 32595725, 2020).
Peri-Implantitis (4 papers, 2020 to 2024). An inflammatory process with loss of supporting bone in the tissues surrounding functioning DENTAL IMPLANTS. "Another TIMP found in peri-implant tissues was TIMP-2, which is also downregulated in peri-implantitis, but it had a less important role in peri-implant disease than TIMP-1." (PMID 37232785, 2023). "A higher concentration of IL-1b, interleukin-8 (IL-8), TNF-α, tissue inhibitor of metalloproteinase-2 (TIMP-2), vascular endothelial growth factor (VEGF), and osteoprotegerin (OPG) have been reported in the peri-implantitis crevicular fluid, in comparison to healthy implants." (PMID 39452426, 2024).